VIM (vimentin)
Diseases named in the same sentence as VIM in open-access papers (continued):
Sharing a sentence is not in itself a finding about the gene and the disease.
tumor (continued). "Through studies of the molecular mechanism, we found that FAM171B contributes to tumor progression by stabilizing vimentin in the cytoplasm." (PMID 37915048, 2023). "CDH1 and VIM gene expression were significantly reduced and increased, respectively, in tumor samples with high CYSLTR1 gene expression." (PMID 36834820, 2023). "Once EMT gene Vimentin or N‐cadherin is activated in tumour metastasis, Dre‐rox recombination blocks ZsGreen expression, and irreversibly converts the label from ZsGreen to tdTomato." (PMID 37060165, 2023). "SOX30 can also inhibit tumor metastasis by upregulating e-cadherin and downregulating n-catherin, vimentin and fibronectin and preventing epithelial-mesenchymal transmission (EMT)." (PMID 38132438, 2023). "The tumor cells showed strong diffuse cytoplasmic immunopositivity for myoglobin and vimentin, and focal staining for desmin." (PMID 37649059, 2023). "Another study indicated that immunization of mice with citrullinated vimentin peptides resulted in anti-tumour effects against subcutaneous B16 melanoma, inducing a CD4+ T-cell response and resulting in an approximate 80% survival rate." (PMID 37778382, 2023). "Vimentin is a mesenchymal marker and plays an vital role in promoting cell migration and is significantly upregulated during tumor metastasis." (PMID 37958455, 2023). "Characterized by markers like α-smooth muscle actin, fibroblast activation protein, and vimentin, CAFs are relentless contributors to facets like tumor expansion, invasion, drug resistance, and overall ECM reconfiguration." (PMID 38140058, 2023). "In the present case, the tumor cells were strongly positive to vimentin, supporting its fibroblastic origin." (PMID 36609451, 2023). "In terms of immunophenotype, this involves tumor cells expressing CKpan and 34ßE12, while the spindle cells are positive for vimentin expression." (PMID 37724114, 2023). "Many of the DEGs were involved in ferroptosis (Ptgs2), enhanced T-cell function (Lef1), regulators of EMT (Zeb1, Zeb2, Vimentin, and Sfrp2), and fibrosis (Col1α1 and Acta2) in the tumor microenvironment." (PMID 36835036, 2023). "Zeb1 expression is accompanied by the downregulation of vimentin, which constrains tumor invasion and migration." (PMID 38132928, 2023). "Repeated treatment of TiY inhibited tumor formation by targeting vimentin-positive cells in tumors with low toxicity to normal cells." (PMID 36923526, 2023). "The secretion of two key molecules in EMT, vimentin and cadherin 3/11, was increased, while proteins involved in tumor immune escape, cell cycle and DNA damage were also increased to varying extent." (PMID 37649614, 2023). "Another study on CRC has found that stromal vimentin expression is significantly correlated with T stage, suggesting its possible involvement in tumor invasion." (PMID 37143134, 2023). "The vaccine is directed against a specific protein, named extracellular vimentin, excreted by the tumor vasculature." (PMID 37568772, 2023). "Western blotting analysis confirmed that NTN4 overexpression downregulated β-catenin, Vimentin, and Bcl-2 expression in the tumor tissues." (PMID 37345154, 2023). "Vimentin helps tumor cells break out from carcinoma in situ and invade blood or lymph arteries, thereby providing them with the potential for proliferation." (PMID 37718450, 2023). "Together, our results demonstrate that vimentin is required for rapid tumor growth, metastasis, and protection from ferroptosis in NSCLC." (PMID 37161053, 2023). "As the next step in the development of recurrence, these tumor cells regain E-cadherin expression and their epithelial cohesive characteristics while expression of vimentin is downregulated; this is called mesenchymal–epithelial reverting transition." (PMID 36867254, 2023). "Immunohistochemical staining revealed the tumor cells were positive for Vimentin, S-100, CD34 and MDM2." (PMID 37670330, 2023).
tumor (continued). "In most cases, tumor samples from patients with high vimentin expression exhibited low MAP17 expression (case 8 and case 39) and samples from patients with low vimentin expression exhibited high MAP17 expression (case 10 and case 21)." (PMID 36737832, 2023). "Vimentin not only plays a role in maintaining cell morphology, movement, and division but also plays a role in pathogen infection, tumor invasion, and signal transduction." (PMID 36912679, 2023). "The IHC staining revealed a significant decrease in the expression of MMP-2, MMP-9, N-cadherin, and Vimentin in DMC-HA-treated tumor tissues." (PMID 38154100, 2023). "Upregulation of vimentin and downregulation of E-cadherin indicated that the tumor cells in the miR-135b-5p-high group possessed a mesenchymal phenotype." (PMID 36755690, 2023). "In MTAP-deficient cells, lower sDMA modification on protein reduces the degradation of vimentin, therefore increasing vimentin expression and ultimately enhancing tumor metastasis." (PMID 37091983, 2023). "The expression of programmed death-ligand 1 (PD-L1), tumor-infiltrating lymphocytes (TILs), E-cadherin, and vimentin in lung cancer tumor microenvironment is known to impact patient survival or response to therapy." (PMID 37340370, 2023). "In the third case (ID6), although there was a concordant expression of vimentin and calponin between primary tumor and 3D culture, discordant expression was observed for actin, since it was present in the primary tumor and not in the cell culture." (PMID 38071286, 2023). "Examining disseminating tumour cells in over 12,000 imaging fields from 74 human oral tumours, we see a significant enrichment of EpCAM, CD24 and Vimentin co-stained cells disseminating beyond the tumour body in metastatic specimens." (PMID 37975646, 2023). "Our results show that VIM gene expression is about 11-fold higher in GBM tissue compared with non-tumour brain tissues and was also significantly higher compared with LGG." (PMID 36765531, 2023). "EMT transformation results in the alteration of epithelial and mesenchymal markers, particularly E-cadherin, N-cadherin, vimentin, and fibronectin, which promote the ability of tumor cells to migrate and spread to nearby or distant areas." (PMID 38068712, 2023). "CRA-induced AAs recognize multiple antigens on the cell surface of CRC tumor cells, such as heat shock proteins, vimentin, ATP synthase, GRP78 and so on." (PMID 37081540, 2023). "According to immunohistochemical analysis (IHC), the tumor cells were diffusely positive for vimentin and had a high multifocal expression of wide-spectrum cytokeratins." (PMID 36673024, 2023). "After transfection with sh-RNA, the expression of Ki-67, N-cadherin, and vimentin in EC9706 cells was lower than that in normal tumor cells, except for E-cadherin." (PMID 37938614, 2023). "The tumor suppressive miR-944 was reported to reduce PA growth and progression by regulating the expression of E-cadherin and vimentin." (PMID 38204968, 2023). "Immunoflourescence-based IHC analysis demonstrated the reduction in E-cadherin and the increase in vimentin expression in FGF-induced tumor sections." (PMID 37222403, 2023). "As expected, although the tumor cells are heterogenous in vimentin level, almost all cells express vimentin protein." (PMID 36672246, 2023). "In the present case, IHC examination of the tumor revealed that vimentin was positively stained, P63, KRT14, S-100 was focally positive, Ki-67(80%), while KRT5/6, KRT7, GFAP, calponin, SMA, KRT-PAN, SOX10, mammaglobin was negative." (PMID 37705036, 2023). "Known for its ability to regulate cytoskeletal organization in various cancer cell types, including HNSC, vimentin is an important protein in tumor invasion and migration." (PMID 38129784, 2023).
tumor (continued). "Using 3D culture models, co-culturing CAFs with down-regulated vimentin along with lung adenocarcinoma cells results in spheroids with reduced formation of invasive branches, suggesting an attenuated ability of tumor cells to migrate out of the spheroids." (PMID 38313431, 2023). "Positivity for vimentin was significantly higher in the unclear tumor border group compared with the clear tumor border group (p = 0.045)." (PMID 37717112, 2023). "The TUNEL Kit and IHC staining assay were used to analyze the apoptosis level, and β-catenin, Ki67, and vimentin expression level of tumor tissues." (PMID 36980687, 2023). "There was a tendency to a greater increase in the proportion of vimentin-positive cells after irradiation at a TD of 10 Gy in patients with partial tumor regression than in patients with complete regression." (PMID 36834676, 2023). "During the early stages of metastasis, tumor cells lose mediators of epithelial adhesion, such as E-cadherin, and exhibit a spindle cell morphology, as well as an increase in N-cadherin and vimentin." (PMID 36721217, 2023). "The expression of TGF‐β and the mesenchymal marker proteins such as N‐Cadherin and VIM in the xenograft tumours were significantly reduced in all treatment regimen groups as determined by both western blot and immunohistochemistry." (PMID 36651490, 2023). "Despite the high levels of vimentin in the tumor cells of TNBC, a commentary should be added with regard to its consistency." (PMID 36769215, 2023). "Vimentin is crucial for establishing front-rear polarity, which is necessary for the efficient migration of tumor cells." (PMID 37161053, 2023). "Through studies on the molecular mechanism, we found that FAM171B contributes to tumor progression by stabilizing vimentin in the cytoplasm." (PMID 37915048, 2023). "Meanwhile, FRMD3 inhibits integrin synthesis by degrading vimentin, resulting in cytoskeletal rearrangement and reduced focal adhesions and affecting the regulation of downstream proteins on tumor cell tumorigenesis, metastasis, and aggressiveness." (PMID 36631457, 2023). "The analysis of vimentin expression in the control and tumor tissues showed a statistically significant difference for all tumor grades (all p < 0.05)." (PMID 36833374, 2023). "Among them, α-SMA+ CAFs had significantly more interaction with multiple tumor cell subtypes (especially vimentin+ α-SMA+ E-cadherin+ tumor cells, cluster_1-3/9)." (PMID 37254126, 2023). "Tumors in group 1 had higher abundance of cells in meta cluster 1 and 5 (vimentin high epithelial cells) than the other tumor groups." (PMID 37146405, 2023). "We have previously validated the strong overexpression of vimentin in the tumor vasculature of solid tumors and demonstrated that vimentin is excreted by the tumor vasculature to support angiogenesis and to escape anti-tumor immunity." (PMID 37568772, 2023). "The epithelial–mesenchymal transition (EMT) plays a significant role in tumor invasion and metastasis, by altering the adhesion molecules produced by cells, while E-cadherin and Vimentin participate in the EMT process." (PMID 36677726, 2023). "Overall, in conventional SCC, vimentin immunostaining identifies stromal cells around and within the tumor nests." (PMID 36675308, 2023). "Vimentin was diffusely and highly expressed in 100% of neoplastic cells in both cases supporting the mesenchymal origin of both tumour." (PMID 37525233, 2023). "At the mechanistic level, Arylquin 1 (a 3-arylquinoline derivative and potent Par-4 secretagogue) binds to vimentin, displaces Par-4 from vimentin and the secreted Par-4 induces paracrine tumor cell apoptosis in PCa cells." (PMID 37091854, 2023). "Further characterization of the models via immunofluorescence revealed an abundance of CD3+ and CD8+ T cells in close proximity to fibroblasts (vimentin stained) and the unlabeled tumor cells (blue aggregates)." (PMID 37190054, 2023).
tumor (continued). "We performed immunofluorescence staining to examine Ext1 and vimentin expression of Tomato-positive cells of MC38 tumor tissue in S100a4-Cre; Ext1f/f; Lsl-tdTomato and control mice." (PMID 36809261, 2023). "IHC analyses showed that overexpression of MIR200CHG significantly upregulated E-cadherin and downregulated vimentin in primary tumor and LN metastasis in vivo." (PMID 38065939, 2023). "To further understand the cellular origin of this increased EMT marker expression, we conducted IHC for EPCAM to stain tumor epithelium as well as VIM and ZEB1 in murine and human samples." (PMID 38153787, 2023). "Vimentin was often highly expressed in the mesenchymal tissue rather than in the tumor, indicating that the expression of NLRP11 and vimentin‐K104Ac was more tumor‐specific." (PMID 37424170, 2023). "High ZEB1, PD-L1, TIMP2, TWIST1, and VIM expression represents a specific gene signature in blood-circulating tumor cells from NMIBC patients." (PMID 37627900, 2023). "Studies have shown that tumor invasion and migration are significantly influenced by altered E-cadherin expression and elevated N-cadherin and vimentin expression." (PMID 38034950, 2023). "IHC staining was performed to detect the expression levels of USP7, YY1, E-cadherin, and vimentin in tumor tissues." (PMID 37408047, 2023). "Tumor sections also stained positive for vimentin and CD31 (also known as PECAM1) markers, which suggested a mixed epithelial phenotype, possibly with epithelial-to-mesenchymal transition (EMT)." (PMID 36579622, 2023). "We performed immunofluorescence staining to examine Ext1 and vimentin expression of Tomato-positive cells of Pan02 tumor tissue in S100a4-Cre; Ext1f/f; Lsl-tdTomato and control mice." (PMID 36809261, 2023). "The immunohistochemistry panel revealed that the tumor cells are positive for vimentin, CD56, CD10, alpha-1-antichymotrypsin, NSE, and β-catenin in all 12 cases." (PMID 38169685, 2023). "In comparison with the Si-NC group, TRIM14 knockdown decreased the percentages of positive TRIM14 and Vimentin cells in the tumor cells." (PMID 37628777, 2023). "During EMT, tumor cells acquire mesenchymal phenotypes, including fibroblast-like morphology, high motility, and vimentin expression, resulting from the downregulation of epithelial hallmarks, including adhesion properties and E-cadherin expression." (PMID 37798461, 2023). "In this study, the clinical and pathological features closely related to the prognosis of HCC and the expression levels of 13 proteins, including GPC3, CK19, and vimentin, in the tumor tissue were selected for multivariate analysis." (PMID 36973651, 2023). "Vimentin staining of feline HNSCC yielded an intensive cytoplasmic signal of tumor cells with patchy distributions in most sections and signals of varying intensity in two cases." (PMID 38003753, 2023). "The tumor tissue comprised spindle cells and epithelioid cells with irregular nuclei, and the immunohistological analysis was positive for vimentin and epithelial membrane antigen, which was consistent with a diagnosis of sclerosing epithelioid fibrosarcoma." (PMID 37270505, 2023). "As we known, VIM was an epithelial-mesenchymal transition biomarker, highly expressed in stromal cell and tumor cell." (PMID 38095634, 2023). "The Increased stromal vimentin expression is thought to reflect the dynamic changes of tumor stroma during progression." (PMID 37749564, 2023). "In contrast with the vector group, TRIM14 overexpression greatly decreased E-cadherin expression and upregulated the profiles of N-cadherin, Snail, and Vimentin in the tumor tissues (p < 0.05)." (PMID 37628777, 2023). "Immunohistochemical expression of diagnostic markers EMA, vimentin, NSE and CD99, and AFP was comparable to the expression observed in the primary tumor." (PMID 38201285, 2023). "In contrast to the expression of hemichannel proteins, which showed a wreath-shaped pattern, vimentin-positive tumor cells exhibited an intracellular distribution." (PMID 36833374, 2023).
tumor (continued). "Subsequent Western blot and immunohistochemistry analyses of the tumor tissues revealed lower expression of E-cadherin and higher expression of N-cadherin and vimentin in response to IGFBP2 overexpression." (PMID 37957694, 2023). "The proportion of vimentin-positive cells was compared with the short-term outcome of treatment (degree of tumor regression 3–6 months after radio- or chemoradiotherapy)." (PMID 36834676, 2023). "The mesenchymal markers ACTA2, CDH2, CDH11, and VIM are involved in proliferation, generation of stem-cell-like cells, and tumor progression." (PMID 37345150, 2023). "In preclinical models, the targeting of vimentin with antibody therapy or vaccination significantly inhibited tumor growth." (PMID 37568772, 2023). "These global vimentin knockout mice lack vimentin expression in tumor cells and tumor microenvironment (TME)." (PMID 37161053, 2023). "These were trained using the CD24+EpCAM+VIM+-positive cell counts for each field of view, separated into tumour body and stroma using our imaging segmentation pipeline." (PMID 37975646, 2023). "The current research evaluated the transcriptional level of EMT markers in BC, and it revealed that ZEB2 and vimentin gene expression levels in tumor samples had significant increases compared to normal samples." (PMID 37088469, 2023). "As exhibited by immunohistochemistry, in contrast with the vector group, the TRIM14 overexpression group had a higher expression of TRIM14, Vimentin, and N-cadherin in the tumor, while E-cadherin was repressed following TRIM14 overexpression." (PMID 37628777, 2023). "High expression of vimentin is observed in primary and metastatic tumours derived from epithelial tissues, and it modulates the metastatic cascade: EMT, invasion and migration." (PMID 37307404, 2023). "Our study suggests that vimentin is related to tumor prognosis, possibly because it is related to the permeability of tumor neovascularization." (PMID 37749564, 2023). "On the other hand, CDH1 and VIM expression were higher in tumor samples with high expression of the CYSLTR2 gene." (PMID 36834820, 2023). "In these panels, cytokeratins and vimentin are applied to discriminate from epithelial and mesenchymal origin of the tumours." (PMID 37525233, 2023). "The stromal (S) and tumor (T) regions were highlighted by vimentin and pan-cytokeratin (PanCK) expression, respectively (left composite)." (PMID 36446524, 2023). "Elevated protein levels of B-catenin, vimentin, and BCL2 have been evidenced to inhibit apoptosis and are frequently associated with epithelial mesenchymal transition (EMT) and tumor metastasis." (PMID 37542131, 2023). "Recent reports indicated that the JNK/P38 MAPK signaling pathway was critical for the tumor EMT and metastasis that regulates the expression of EMT-associated proteins, such as E-cadherin and vimentin." (PMID 37367670, 2023). "In the EMT process, which it happens tumor migration and proliferation., the expression of Vimentin and N-cad factors increases, and E- cadherin decreases." (PMID 37361568, 2023). "Immunohistochemistry reveals tumor cells’ reactivity to vimentin, desmin, actin, myoglobin, MyoD1, and myogenin." (PMID 36777814, 2023). "Vimentin is an important component of the intermediate filament protein family and a biomarker for predicting tumour metastasis, which is closely related to the invasion and metastasis of various malignant tumours." (PMID 36994917, 2023). "First, we assessed the expression of the epithelial and mesenchymal markers, E-cadherin and vimentin, respectively, in the tumor tissue and in each cell line." (PMID 37798461, 2023).